IL33 (interleukin 33)
Diseases named in the same sentence as IL33 in open-access papers (continued):
Sharing a sentence is not in itself a finding about the gene and the disease.
Anxiety (continued). "Together this means that the authors still cannot claim “our study suggests that IL-33 influences anxiety-related and social behaviors by modulating neuronal activities in relevant brain regions” (abstract)." (PMID 29379874, 2017). "Future studies on brain-specific deletion of the Il33 gene will address the contribution of central and peripheral IL-33 to anxiety-related and social behaviors." (PMID 29379874, 2017). "Consistent with these behavioral changes, we observed that the expression of an immediate early gene, c-Fos, was significantly altered in brain regions related to anxiety in Il33−/− mice." (PMID 29379874, 2017). "In this study, we reported a novel role of the nuclear alarmin IL-33 in the regulation of anxiety-related and social behaviors in mice." (PMID 29379874, 2017). "In Il33−/− mice, c-Fos immunoreactivity was altered in several brain areas, including those related to anxiety, after a stressful behavioral assay." (PMID 29379874, 2017). "Moreover, IL-33 regulates microglial activation and polarization, potentially affecting anxiety control in the basolateral amygdala via the IL-33/ST2/NF-κB pathway." (PMID 39273641, 2024). "Another study found that in LPS-induced anxiety models, IL33 expression was significantly upregulated in the BLA, while overexpression of IL33 in astrocytes inhibited BDNF expression through the NF-κB signaling pathway, affecting the synaptic transmission of GABA and causing anxiety disorders." (PMID 36232376, 2022). "As IL-33 is expressed in areas of the limbic system such as the amygdala, it is not surprising that IL-33 deficiency has been associated with anxiety-related behaviors." (PMID 32486265, 2020). "In one study, IL-33-deficient C57BL/6 mice demonstrated anxiety-related behaviors measured by the open field test that is commonly used to assess locomotor activity levels, as well as anxiety and willingness to explore." (PMID 32486265, 2020). "One potential gap in the knowledge is whether there is a significant effect of mouse background on the anxiety phenotype seen in IL-33 mice of a C57BL/6 background." (PMID 32486265, 2020). "Thus, there are at least three potential mechanisms by which IL-33 affects anxiety and social novelty recognition." (PMID 29379874, 2017). "The immunoreactivity of c-Fos proteins, an indicator of neuronal activity, was altered in several brain regions implicated in anxiety-related behaviors, such as the medial prefrontal cortex (mPFC), amygdala, and piriform cortex (PCX), in Il33−/− mice after the EPM." (PMID 29379874, 2017). "In this study, we provide evidence that IL-33 is involved in anxiety-related and social behaviors." (PMID 29379874, 2017). "The mechanisms by which IL-33 influences the development and/or maturation of multiple neuronal circuits linked to anxiety and social recognition-related behaviors are not clear at this moment." (PMID 29379874, 2017). "In the absence of such data, the study strongly suggests that “IL33 deficiency dysregulates the development and/or maturation of multiple neuronal circuits relevant to anxiety and social behaviors” (discussion lines 337-339)." (PMID 29379874, 2017). "Thus, our study has revealed that Il33−/− mice exhibit multiple behavioral deficits, such as reduced anxiety and impaired social recognition." (PMID 29379874, 2017). "OPCs and astrocytes are known to produce interleukin 33 in the brain, and the performance of interleukin 33 knockout mice in the elevated plus maze and open field test is indicative of reduced anxiety, suggesting that increased interleukin 33 release could conversely increase anxiety." (PMID 30524235, 2018). "The analysis of IL-33 role in animal behavior revealed that mice lacking of the interleukin undergo to a reduction of anxiety, but they also develop an impaired social recognition." (PMID 33810498, 2021). "Here, we report that mice lacking IL-33 (Il33−/− mice) showed reduced anxiety-like behaviors and impaired social novelty recognition." (PMID 29379874, 2017).
Anxiety (continued). "In the elevated plus maze (EPM) and the open field test (OFT), mice lacking IL-33 (Il33−/− mice) exhibited reduced anxiety-like behaviors compared to wild-type (WT) mice." (PMID 29379874, 2017). "The fact that social novelty detection is also impaired in IL-33 KO mice raises the possibility that there are general learning and memory deficits in these mice and indicates that behavioral alterations are not specific to anxiety-related behaviors." (PMID 29379874, 2017). "Moreover, whether IL-33 has a direct or downstream effect on anxiety-related behavior is not known." (PMID 32486265, 2020).
bronchiolitis (14 papers, 2017 to 2025). Inflammation of the bronchioles characterized by swelling of the bronchioles and mucus accumulation. "Infants hospitalized with HRSV-caused bronchiolitis had high levels of IL-13 and IL-33, which were associated with the need for ventilation." (PMID 37239461, 2023). "Notably, a 2015 study highlighted how children with a familiar history of atopy exhibited high IL-33 expression in NPAs during bronchiolitis caused by RSV." (PMID 40872787, 2025). "Similarly, another study associated increased IL-33 levels with cases of bronchiolitis, especially in instances of co-infection." (PMID 40872787, 2025). "Taken together, these results indicate that IL-33 could be a good biomarker to determine the severity and prognosis during bronchiolitis caused by hRSV." (PMID 31214165, 2019). "Our group, in a previous study 39, detected nasal IL-33 cytokine secretion in infants < 2 years of age hospitalized with bronchiolitis, with significantly higher detection rate in patients with HRV-infection." (PMID 35534518, 2022). "NF-B/IL-33/ST2 axis mediated the level of Th2 cytokines and the number of bronchoalveolar lavage fluid cells induced by RSV, and NF-B/IL-33/ST2 inhibition during RSV infection alleviated acute bronchiolitis in mice." (PMID 35592688, 2022). "In conclusion, all of these findings seem to support the correlation between RSV infection and an increase in IL-33 release that, in turn, is crucial for induction of atopy, airway hypersensitivity, and worse-outcome bronchiolitis." (PMID 35327516, 2022). "The study was aimed at investigating the role of NF-κB/IL-33/ST2 axis on RSV-induced acute bronchiolitis." (PMID 34395633, 2021). "In conclusion, we confirmed that NF-κB/IL-33/ST2 axis is mediated the acute bronchiolitis by RSV infected." (PMID 34395633, 2021). "Previous studies have shown that NF-κB is involved in the process of RSV-induced acute bronchiolitis, and NF-κB inhibitor dimethyl fumarate inhibited IL-33 production, but its specific mechanism is unclear." (PMID 34395633, 2021). "The bronchiolitis group serum IL-5, IL-9, IL-13, IL-33, TSLP protein levels were higher than the normal control group." (PMID 33514798, 2021). "IL-33 level was significantly elevated, and Th1/Th2 ratio is imbalance after in infants with acute bronchiolitis." (PMID 34395633, 2021). "Our study found that compared with the control group, the levels of IL-17RB, TSLP, and IL-33 in the bronchiolitis group were significantly increased." (PMID 33514798, 2021). "Acute bronchiolitis induced by RSV in a mouse model is attenuated after inhibition of NF-κB/IL-33/ST2 pathway." (PMID 34395633, 2021). "The ST2 protein expression was positively correlated (r = 0.669, p < 0.001) with IL-33 production in acute bronchiolitis cases." (PMID 34395633, 2021). "Firstly, the expression of IL-33 in serum of acute bronchiolitis infants infected by RSV was examined by ELISA assay; we found that IL-33 concentrations in AVB infants were significantly increased compared to normal subjects." (PMID 34395633, 2021). "In this study, we confirmed that the ST2 gene expression was positively correlated with IL-33 production in acute bronchiolitis cases." (PMID 34395633, 2021). "Yet the amount of evidence related to involvement of IL-33 in the pathogenesis of RSV-mediated bronchiolitis justifies the evaluation of those therapies." (PMID 32397226, 2020). "The elevation of IL-33 levels detected in nasopharyngeal aspirates (NPAs) suggests that it may be involved in the inflammatory processes that occur during bronchiolitis." (PMID 40872787, 2025). "We confirmed that inhibition of NF-κB/IL-33/ST2 axis could attenuate acute bronchiolitis by RSV infected." (PMID 34395633, 2021). "Moreover, we demonstrated that NF-κB/IL-33/ST2 axis is involved in the RSV-induced acute bronchiolitis." (PMID 34395633, 2021). "Therefore, IL-17RB, TSLP, IL-33 may participate in the development of bronchiolitis through ILC2s cells." (PMID 33514798, 2021).
bronchiolitis (continued). "However, the role of IL-33/ST2 pathway on RSV-induced acute bronchiolitis and its molecular mechanism is unknown." (PMID 34395633, 2021). "The role of IL-33 in the immune response, particularly in relation to RSV infection and bronchiolitis, is significant and multifaceted." (PMID 40872787, 2025). "In our study, we demonstrated that the levels of IL-33 and Th2-related cytokines IL-4 and IL-10 in RSV infected acute bronchiolitis in serum of infants were significantly increased." (PMID 34395633, 2021). "Immunostaining results showed that the abundances of IL-33, ST2, and p65 were all increased in acute bronchiolitis induced by RSV than NC groups." (PMID 34395633, 2021). "In our present study, we explored the expression of IL-33 in serum of acute bronchiolitis infants and in lung tissues of RSV-induced mice and investigated its role on Th1/Th2 cell ratio in acute bronchiolitis infants and RSV infected mice." (PMID 34395633, 2021). "It was reported that the production of Th2 cytokines IL-4 and IL-10 was promoted by IL-33, and Th2 immune response was described to influence the pathogenesis of respiratory syncytial virus (RSV) acute bronchiolitis." (PMID 34395633, 2021). "The second study reported that neonatal mice deficient in interferon-β promotor stimulator-1 (IPS-1) that were PVM-infected and subsequently re-infected with PVM developed severe bronchiolitis marked by release of HMGB1 and IL-33." (PMID 32397226, 2020). "Our findings, in a recent study conducted in hospitalized infants with bronchiolitis and in healthy controls, showed that nasal TSLP and IL-33 are detected more frequently in viral coinfections than in single infections." (PMID 29206851, 2017). "In summary, the accumulating evidence suggests that IL-33 is pivotal in driving the Th2 immune response in RSV infections and serves as a potential biomarker for assessing disease severity and prognosis in infants suffering from bronchiolitis." (PMID 40872787, 2025). "It is worth noting that no patient with bronchiolitis but with negative viral detection had detectable levels of nasal TSLP or IL-33, suggesting that the release of these proteins may be mediated by respiratory viruses." (PMID 29206851, 2017). "However, little or no change was observed for IL33 and MCP1, at difference to previous results from bronchiolitis hospitalized patients." (PMID 36561744, 2022).
rhinitis (14 papers, 2011 to 2024). An inflammation of the mucous membrane lining the nose, usually associated with nasal discharge. "With further loss of microbiome complexity, the IL-33 pathway becomes activated, leading to multimorbidity (asthma and rhinitis) and polysensitization in individuals who are genetically predisposed." (PMID 39596052, 2024). "Genetic polymorphism in ST2 or IL-33 was found in patients with rhinitis and rhinosinusitis." (PMID 38137606, 2023). "Toll-like receptors and IL-17-mediated signalling were identified in rhinitis alone, while IL-33 was identified in rhinitis in multimorbidity." (PMID 37573373, 2023). "Serum IL-33 levels were significantly higher in patients with rhinitis compared to healthy subjects." (PMID 38137606, 2023). "In particular, alarmin cytokines such as IL-25, IL-33, and TSLP are strongly associated with the development of rhinitis due to PM exposure." (PMID 35378908, 2022). "Particularly, in the context of rhinitis/rhinosinusitis and T-cell inflammation, there is scant data for a role of IL-33." (PMID 25932636, 2015).
tendinopathy (14 papers, 2015 to 2026). "In our study, the difference of serum levels of IL-6, IL-15, IL-33, and IL-17 are noted before and after serum biomarkers can reflect systemic inflammatory responses, metabolic changes, and tissue remodeling associated with tendinopathy." (PMID 39690426, 2024). "IL-33 is an “alarmin” expressed in early tendinopathy, tendon injury and subsequent tissue remodeling." (PMID 37588508, 2023). "In regard to the indirect regulation of IL-33 by microRNA, miR-29a has also been described as a direct negative regulator of sST2 mRNA in a murine model of tendinopathy, therefore, miR-29a inhibits sST2 production affecting the activation of IL-33/ST2 axis." (PMID 31824476, 2019). "IL33—a cytokine having a pivotal role in innate and acquired immune responses—was described to be important in early tendinopathy." (PMID 29385715, 2018). "We also provide evidence for a hitherto unreported role of IL-33 in the initial steps that lead to the important clinical entity of tendinopathy." (PMID 25857925, 2015). "Early tendinopathy tissues exhibited significantly greater staining for IL-33 and ST2 compared with torn tendon or control biopsies." (PMID 25857925, 2015). "Our data implicate IL-33 as an alarmin in early tendinopathy and, importantly, our biomechanical data suggest that such an expression has a pathogenically relevant role." (PMID 25857925, 2015). "Utilizing the common human condition tendinopathy as a model system to explore the cross-regulation of immediate inflammation and matrix synthesis by miRNA we observed that elevated IL-33 expression is a characteristic of early tendinopathy." (PMID 25857925, 2015). "Similarly, studies in tendinopathy models identified sST2 as one of the targets of miRNA-29; increased IL-33 release during tendon injury was reported to downregulate miRNA-29a expression, thereby leading to elevated sST2 levels." (PMID 41614943, 2026). "Specifically, S100A9 and HIF-1α may have pro-inflammatory effects in tendon disease, nuclear IL-33 may be protective against pro-inflammatory stimuli and HMGB1 may have a potential role in tendon healing." (PMID 28761710, 2017). "Interleukin-33-dependent radiation response could potentially be compared with an early tissue insult in tendinopathy." (PMID 28702024, 2017). "Additionally, IL-33 has a potentially protective role in healthy tendons that is lost with the onset of tendon disease." (PMID 28761710, 2017). "On the basis of this work, we propose IL-33 as an influential alarmin in the unmet clinical area of early tendon injury and tendinopathy, which may be important in the balance between reparation and degeneration." (PMID 25857925, 2015). "IL-33 then drives the matrix degeneration and proinflammatory cytokine production, propelling the tendon towards a pathological state such as that seen in early tendinopathy biopsies." (PMID 25857925, 2015). "We first investigated IL-33 expression in human tendinopathy using our previously developed model." (PMID 25857925, 2015). "IL33, soluble and membrane-bound ST2 transcripts were significantly upregulated in early tendinopathy compared with control or torn tendon biopsies." (PMID 25857925, 2015).
Cirrhosis (13 papers, 2015 to 2025). A chronic disorder of the liver in which liver tissue becomes scarred and is partially replaced by regenerative nodules and fibrotic tissue resulting in loss of liver function. "Genetic studies have identified associations between IL-33 gene variants and susceptibility to HBV-related cirrhosis." (PMID 39995661, 2025). "We observed that C-C motif chemokine ligand 2 (CCL2), interleukin (IL)-18, and interleukin (IL)-33 were elevated in the circulation of patients with either acute infection (a-HBV) or early cirrhosis (cir-HBV), in contrast to healthy individuals (HI)." (PMID 40565198, 2025). "Cytokine levels of IFN-α2, IFN-γ, TNF-α, IL-6, IL-8, IL-10, IL-17A, IL-18, IL-23, and IL-33 were significantly elevated in patients with decompensated cirrhosis compared to patients with compensated cirrhosis." (PMID 38077228, 2023). "Intranasal IL-33 pre-treatment also attenuated concanavalin A-induced acute hepatitis and cirrhosis." (PMID 34305911, 2021). "In primary biliary cirrhosis (PBC), an autoimmune liver disease with complications such as cirrhosis, liver failure, and hepatoma carcinoma, the serum IL-33 level of patients was positively correlated with severity." (PMID 29180837, 2017). "IL33-rs4742170C, rs1048274G, and rs10975519C variants may serve as potential biomarkers for diagnosing HBV-associated cirrhosis." (PMID 39995661, 2025). "Increased levels of C-C motif chemokine ligand 2 (CCL2), interleukin (IL)-18, IL-33, and citrullinated histone H3 (CitH3)—an accurate marker of neutrophil extracellular traps (NETs)—were detected in the circulation of patients with acute infection or early cirrhosis." (PMID 40565198, 2025). "Here, patients with decompensated cirrhosis had significantly higher serum levels of Int-α2, Int-γ, TNF-α, IL-6, IL-8, IL-10, IL-23, and IL-33 compared to compensated patients, both in blood obtained from hepatic and jugular veins." (PMID 38077228, 2023). "IL-33 appears to represent a valuable biomarker of tissue injury and the ongoing activity of ILC2s is triggered by IL-33, targeting either IL-33 or ILC2-released cytokines may provide new therapeutic approaches to limit fibrosis and cirrhosis." (PMID 30999584, 2019).
diabetic nephropathy (13 papers, 2016 to 2025). "Based on the implication of IL-33 in diabetic kidney diseases, this observation warrants the inclusion of the IL-33/IL1RL1 axis in further investigations." (PMID 36672735, 2023). "Although the IL-33/ST2 axis is known to be involved in diabetic kidney disease or related nephropathy, its role and molecular mechanisms remain poorly understood in terms of DN." (PMID 38053041, 2023). "Calycosin ameliorated glomerulosclerosis and interstitial fibrosis in diabetic nephropathy by downregulating the IL33/ST2 signaling pathway." (PMID 35784691, 2022). "This literature review has retrieved a handful of articles directly dealing with the IL-33/ST2 axis involvement in diabetic kidney disease or related nephropathy." (PMID 30769901, 2019). "Furthermore, the relationship between IL-33 and diabetic nephropathy was assessed, where decreased IL-33 levels in individuals with nephropathy were observed." (PMID 39171751, 2024). "Interleukin-33 (IL-33) and homocysteine (Hcy) were found to be up-regulated in patients with diabetic nephropathy (DN), and the present study aimed to investigate whether metformin (MT) can influence the serum levels of IL-33 and Hcy in patients with DN." (PMID 31535033, 2019). "The role for sST2 appears to be stronger than the role of IL-33, as demonstrated by the lack of association between the increased IL-33 levels and kidney injury in diabetic nephropathy, with such increase possibly associated with diabetic disease." (PMID 30769901, 2019). "Therefore, in the present work, a literature review was conducted, covering the period from 1 January 2000 to 30 November 2018, in PubMed, ScienceDirect, and Google Scholar database, to assess the involvement of the IL-33/ST2 axis in diabetic kidney disease." (PMID 30769901, 2019). "IL-33 from necrotic cells might induce autophagy, which can further balance the effects of increased apoptosis secondary to contrast-induced nephropathy in diabetic kidney disease." (PMID 27579324, 2016). "Despite the relatively low number of studies published to date, the link between IL-33/ST2 axis and diabetic kidney disease, appears to be more clear, with significant correlations with the disease stage." (PMID 30769901, 2019).